DSCAM (DS cell adhesion molecule)
Description:
Cell adhesion molecule that plays a role in neuronal self-avoidance. Promotes repulsion between specific neuronal processes of either the same cell or the same subtype of cells. Mediates within retinal amacrine and ganglion cell subtypes both isoneuronal self-avoidance for creating an orderly dendritic arborization and heteroneuronal self-avoidance to maintain the mosaic spacing between amacrine and ganglion cell bodies. Receptor for netrin required for axon guidance independently of and in collaboration with the receptor DCC. Might also collaborate with UNC5C in NTN1-mediated axon repulsion independently of DCC (By similarity). In spinal cord development plays a role in guiding commissural axons projection and pathfinding across the ventral midline to reach the floor plate upon ligand binding. Mediates intracellular signaling by stimulating the activation of MAPK8 and MAP kinase p38. Adhesion molecule that promotes lamina-specific synaptic connections in the retina: expressed in specific subsets of interneurons and retinal ganglion cells (RGCs) and promotes synaptic connectivity via homophilic interactions (By similarity).
Synonyms: CHD2-42; CHD2-52; CHD2
Tractability: Antibody: UniProt places it where antibodies can reach, with high confidence; its Gene Ontology location is reachable by antibodies, with high confidence; UniProt predicts a signal peptide or a membrane-spanning region. PROTAC: ubiquitination databases record sites on it.
Gene: Protein-coding gene on chromosome 21 (40,010,999 to 40,847,158, reverse strand). Ensembl gene ENSG00000171587.
Subcellular location: Secreted (Isoform Short); Cell membrane (Isoform Long); Cell projection, axon; Cell projection, dendrite; Cell projection, growth cone; Synapse
Subcellular location (Human Protein Atlas): Golgi apparatus; Cytosol
Pathways (Reactome):
Developmental Biology: DSCAM interactions
Gene Ontology:
Molecular function: netrin receptor binding; protein binding; cell-cell adhesion mediator activity; protein tyrosine kinase binding
Biological process: positive regulation of axon extension involved in axon guidance; positive regulation of phosphorylation; axon guidance; camera-type eye photoreceptor cell differentiation; cell adhesion; central nervous system development; dendrite self-avoidance; homophilic cell-cell adhesion; negative regulation of cell adhesion; nervous system development; retina layer formation; synapse assembly; netrin-activated signaling pathway
Cellular component: axon; dendrite; growth cone; membrane; neuronal cell body; plasma membrane; synapse; extracellular region
Genetic constraint (gnomAD): Loss-of-function variants: 47 observed, 214.06 expected, observed/expected ratio (o/e) 0.22, 90% interval 0.17 to 0.28. The upper end of that interval is the gene's LOEUF score, 0.28, which puts it in group 1 of 6, group 1 being the genes least tolerant of losing a copy. Missense variants: 2,051 observed, 2,681.6 expected, observed/expected ratio (o/e) 0.76, 90% interval 0.74 to 0.79. Synonymous variants: 1,043 observed, 1,043.6 expected, observed/expected ratio (o/e) 1, 90% interval 0.95 to 1.05.
Homologues: Orthologues: chimpanzee DSCAM (100% identical), macaque DSCAM (99% identical), dog DSCAM (99% identical), mouse Dscam (98% identical), rat Dscam (98% identical), pig DSCAM (98% identical), guinea pig DSCAM (98% identical), tropical clawed frog dscam (90% identical), zebrafish dscamb (79% identical), zebrafish dscama (79% identical). Paralogues in human: DSCAML1 (61% identical), MXRA5 (17% identical), IGSF10 (17% identical), HMCN2 (15% identical), SDK2 (12% identical), SDK1 (11% identical), NEO1 (11% identical), ROBO1 (10% identical), DCC (10% identical), ROBO3 (10% identical), ROBO2 (10% identical), PTPRQ (9% identical), and 24 more.
Diseases named in the same sentence as DSCAM in open-access papers:
DSCAM is named in the same sentence as 63 diseases in open-access papers, as found by Europe PMC text mining. Sharing a sentence is not in itself a finding about the gene and the disease. The quoted sentences say what the papers report.
Down syndrome (34 papers, 2010 to 2026). "DSCAM occupies a 1-Mb locus in the original Down syndrome critical region on chromosome 21q22 and encodes a neuronal cell adhesion molecule of importance for brain and eye development." (PMID 42063257, 2026). "For example, the first data obtained for Down syndrome, the most frequent cause of ID, confirms the hyperactivation of the DsCam/PAK1 module in patient-derived iPSCs and highlight the possibility to target PAKs in this disease." (PMID 36937657, 2023). "This study shows that the excessive number of inhibitory synapses in the neocortex of Down syndrome mouse models is caused by increased levels of Down Syndrome Cell Adhesion Molecule (DSCAM)." (PMID 37079499, 2023). "DSCAM is located on chromosome 21 in humans; an extra copy of chromosome 21 causes Down syndrome (DS)." (PMID 34848499, 2022). "Recently, DSCAM (Down syndrome CAM) was found to be one of the genetic risk factors for autism in a large-scale genome-wide association study." (PMID 34848499, 2022). "DSCAM has also been identified as a predisposing locus for Hirschsprung’s disease that is often observed in association with Down syndrome." (PMID 30901340, 2019). "Germline mutations in DSCAM have been reported in Down's syndrome and in congenital cardiac malformations." (PMID 29190660, 2017). "In addition to its link with Down syndrome, DSCAM is a strong ASD risk gene recurringly identified in various genome association studies." (PMID 36466804, 2022). "Although signaling pathways are important in the establishment and maintenance of motor circuits, the role of DSCAM, a cell adherence molecule associated with Down syndrome, has only recently been investigated in the context of motor control and locomotion in the rodent." (PMID 34445216, 2021). "Human DSCAM is located within the DS critical region of chromosome 21 (duplicated in Down Syndrome patients), and mutations or copy-number variations of this gene have also been associated to Fragile X syndrome, intellectual disability, autism, and bipolar disorder." (PMID 33585465, 2020). "The DSCAM gene was first characterised as encoding a cell adhesion molecule; a member of the immunoglobulin superfamily of cell surface proteins, in a study which identified it as a Down syndrome-related gene." (PMID 30901340, 2019). "Thus, the wiring of functional neural circuits during embryonic development requires coordinated organization between developing axon and dendritic arbors, a process that is dependent on molecules that have been implicated in Down syndrome and autism, such as DSCAM." (PMID 30219101, 2018). "For instance, overexpression of DSCAM, which occurs in Down syndrome, has been shown to drive an increase in inhibitory connections in the cortex of Down syndrome mouse models." (PMID 39294095, 2024). "Further studies revealed abnormalities in the DSCAM signalling pathway, and knockdown of the DSCAM gene or inhibition of the PAK1 signalling pathway using CRISPR/CAS9 rescued the phenotype related to cortical developmental defects in Down's syndrome." (PMID 39258535, 2024). "Down syndrome cell adhesion molecule (DSCAM) is located on human chromosome 21 and triplicated in Down syndrome." (PMID 36702556, 2023). "DSCAM is expressed in the nervous system of invertebrates and vertebrates, as well as a candidate gene for Down syndrome and congenital heart disease (DSCHD)." (PMID 37539343, 2023). "The DSCAM gene is located on chromosome 21q22.2-q22.3 in the Down Syndrome Critical Region (DSCR) and encodes the Down Syndrome Cell Adhesion Molecule (DSCAM), an immunoglobulin-superfamily member adhesion molecule." (PMID 35740506, 2022). "DSCAM overexpression leads to congenital heart defects and is probably responsible for the congenital heart defects observed in Down syndrome patients." (PMID 34895303, 2021). "Down syndrome cell adhesion molecule (DSCAM) is located within the Down syndrome critical region of chromosome 21." (PMID 28513774, 2017).
Down syndrome (continued). "Various studies have demonstrated a relationship between DSCAM and neurobehavioral phenotype of Down’s syndrome which includes working memory deficit." (PMID 25608650, 2015). "Ts65Dn mice are trisomic for two thirds of the human chromosome 21 homologs in the mouse, including DSCAM, and have cognitive defects that are consistent with Down syndrome." (PMID 26106310, 2015). "Our results reveal the involvement of DSCAM as a HSCR susceptibility locus, both in Down syndrome and HSCR isolated cases." (PMID 23671607, 2013). "In the male bipolar disorder study the best association result was received for a SNP placed in intron 21 in the gene coding for Down syndrome cell adhesion molecule (DSCAM) a gene known to be involved in Down syndrom." (PMID 22389694, 2012). "The marker rs6517590 is placed in intron 21 in the gene coding for Down syndrome cell adhesion molecule (DSCAM), which is highly important for neural development and contributes to the disease mechanisms in Down syndrome." (PMID 22389694, 2012). "DSCAM and RIPK4 have known relations to Down’s syndrome; since the association of Down's syndrome and leukemia has been documented for over 70 years, it is not surprising that DSCAM and RIPK4 are also grouped in this cluster." (PMID 21044360, 2010). "While the overexpression of DSCAM may be contributing to cognitive impairments observed in Down syndrome, its underexpression could be a pathway to autistic‐like phenotypes." (PMID 39294095, 2024). "Analysis of rare segmental trisomies of chromosome 21 suggested that duplication of DSCAM and the contiguous COL6A1 and COL6A2 genes may cause septal abnormalities and other Down Syndrome-related CHD lesions, including BAV." (PMID 37961530, 2023). "Indeed, analysis of a mouse model of Down syndrome showed that DSCAM regulates eye-specific segregation of retinogeniculate projections at the target, in the dorsal lateral geniculate nucleus." (PMID 35422013, 2022). "The gene coding for DSCAM has been mapped to chromosome 21q22.12 → q22.3, commonly duplicated in Down syndrome patients, and its upregulation has been linked to altered neuronal circuits and learning and behavioral abnormalities in early studies on the animal models of Down syndrome." (PMID 36466804, 2022). "Down Syndrome (DS) Cell Adhesion Molecules (DSCAMs) represent a small group of transmembrane proteins of the immunoglobulin superfamily comprising, in vertebrates, DSCAM and its paralogue DSCAM-like 1 (DSCAML1)." (PMID 33585465, 2020). "Moreover, analysis of a mouse model of Down syndrome shows that DSCAM organizes the segregation of ipsilateral and contralateral retinal axons in the dorsal lateral geniculate nucleus." (PMID 30219101, 2018). "Furthermore, the interplay between CYYR1 and DSCAM leads us to the hypothesis that CYYR1 affects leukemia through Down’s syndrome." (PMID 21044360, 2010). "The overexpression of HSA21 genes like DSCAM, RCAN1, and DYRK1A in Down syndrome disrupts calcium homeostasis, primarily by suppressing the calcineurin pathway." (PMID 40964031, 2025). "Down syndrome (DS) and autism spectrum disorders (ASD) are two common neurodevelopmental diseases, the cognitive deficits of which are frequently correlated with aberrant DSCAM expression." (PMID 40385132, 2025).
autism (8 papers, 2012 to 2025). Persistent deficits in social interaction and communication and interaction as well as a markedly restricted repertoire of activity and interest as well as repetitive patterns of behavior. "Abnormal expression of DSCAM is associated with human diseases such as Down syndrome (DS), autism, and certain immune disorders." (PMID 40370466, 2025). "Among genes previously implicated in autism or schizophrenia by exome screening, DSCAM and FOXP1 show evidence for rare coding variant association with left-handedness." (PMID 38565598, 2024). "In mice, either neuron- and astrocyte-specific or pyramidal neuron-specific DSCAM deficiencies resulted in autism-like behaviors and enhanced spatial memory." (PMID 34848499, 2022). "Further research, including whole-genome sequencing, exome sequencing, and targeted sequencing, has shown that DSCAM is a strong autism risk gene." (PMID 34848499, 2022). "Together, these results demonstrate that DSCAM deficiency in pyramidal neurons also induces autism-like behaviors and enhanced spatial memory." (PMID 34848499, 2022). "Precocious spines in DSCAM-deficient mice showed increased glutamatergic transmission in the developing cortex and induced autism-like behaviors, such as social novelty deficits and repetitive behaviors." (PMID 34848499, 2022). "The autism-associated gene DSCAM (Down syndrome cell adhesion molecule) showed significant association with left-handedness after Bonferroni correction for 43 tests (strict set, beta = 0.17, P = 3.6 × 10−4 uncorrected: broad set, beta = 0.15, P = 5.5 × 10−4 uncorrected)." (PMID 38565598, 2024). "The present study suggests that rare, coding variants in these genes are also relevant to left-handedness, which raises the possibility that altered development of the brain’s left-right axis is part of the etiology of autism when caused by DSCAM or FOXP1 mutations." (PMID 38565598, 2024). "Our research demonstrates that DSCAM negatively modulates spine maturation, and that DSCAM deficiency leads to excessive spine maturation and autism-like behaviors, thus providing new insight into a potential pathophysiological mechanism of autism." (PMID 34848499, 2022). "DSCAM-deficient mice with increased spatial memory might belong to the subset of autism mouse models with high functions." (PMID 34848499, 2022). "Finally, DSCAM-deficient mice exhibited autism-like behaviors, including impaired social novelty, increased circling and grooming time, and improved spatial memory." (PMID 34848499, 2022). "Recently, DSCAM (Down syndrome cell adhesion molecule) was found to be a high-risk gene for autism." (PMID 34848499, 2022). "Our results showed that loss of DSCAM in pyramidal neurons induced autism-like behaviors in mice." (PMID 34848499, 2022). "Thus, DSCAM might be a repressor that prevents premature spine maturation and excessive glutamatergic transmission, and its deficiency could lead to autism-like behaviors." (PMID 34848499, 2022). "In our autistic model of DSCAM-deficient mice, early spine maturation in DSCAM-deficient neurons contributed to increased excitatory synaptic transmission, which might impair the E/I balance and lead to autism-like behaviors." (PMID 34848499, 2022). "Therefore, we hypothesized that DSCAM mediates synapse development and that its deficiency can cause autism." (PMID 34848499, 2022). "Additionally, some studies have concluded that DSCAM may act as an inhibitory factor that prevents premature maturation of the spinal cord and excessive glutamatergic transmission, with its deficiency potentially leading to autism-like behaviors." (PMID 40370466, 2025). "Furthermore, we generated DSCAM-deficient mice to validate whether the deletion of DSCAM in neurons would result in abnormal spine maturation and altered synaptic transmission, as well as autism-like behaviors." (PMID 34848499, 2022).
autism (continued). "In DSCAM-deficient mice, this inhibition of the NLGN1-NRXN1β interaction was removed, and resulted in premature spine maturation, which ultimately led to autism-like behaviors and enhanced spatial memory." (PMID 34848499, 2022). "In this study, we provided evidence that DSCAM serves as a repressor for the NLGN1-NRXN1β interaction, and that its deficiency leads to premature spine maturation and excessive glutamatergic transmission, inducing autism-like behaviors." (PMID 34848499, 2022). "However, it remains unknown exactly how DSCAM contributes to autism." (PMID 34848499, 2022).
colorectal cancer (8 papers, 2018 to 2024). A primary or metastatic malignant neoplasm that affects the colon or rectum. "In addition, DSCAM and deleted in colorectal carcinomas (DCC) are both receptors of netrin-1, which serves as an important axon guidance cue during neural development." (PMID 34136475, 2021). "Our scRNA-seq data revealed prominent expression of deleted in colorectal cancer (DCC) and DSCAM, and weaker expression of Unc5c, Unc5D, and Neogenin." (PMID 39569362, 2024). "The UNC5 protein is implicated in the repulsive netrin-mediated axon guidance through heterodimerization with Deleted in Colorectal Cancer (DCC) for long-range repulsion, and with Down syndrome cell adhesion molecule (DSCAM) for short-range repulsion." (PMID 33573025, 2021). "Netrin family activity is mediated by several receptors, including uncoordinated 5A-D (UNC5A-D), deleted in colorectal cancer (DCC), its ortholog neogenin, and the Down syndrome cell adhesion molecule (DSCAM)." (PMID 30532711, 2018).
Hirschsprung disease (5 papers, 2013 to 2023). Hirschsprung disease (HSCR) is a congenital intestinal motility disorder that is characterized by signs of intestinal obstruction due to the presence of an aganglionic segment of variable extent in the terminal part of the colon. "For example, DSCAM cooperates with COL6A2 in congenital heart defects and may interact with BACE2 to increase susceptibility to Hirschsprung disease." (PMID 37712356, 2023).
Intellectual disability (5 papers, 2012 to 2026). "Singleton individuals, both born to first-cousin parents, with intellectual disability and homozygous DSCAM loss-of-function variants were reported in 2017 and in 2021, the latter also presenting with nystagmus and visual impairment." (PMID 42063257, 2026). "Mutations or copy-number variants affecting DSCAM have also been associated with intellectual disability and schizophrenia, and this gene might additionally contribute to the phenotype of Down’s syndrome." (PMID 38565598, 2024). "It has been demonstrated that the overexpressed DSCAM is likely related to intellectual disability, which is the most prominent feature of DS." (PMID 40385132, 2025).
bipolar disorder (4 papers, 2012 to 2024). A disorder of the brain that causes unusual shifts in mood, energy, activity levels and the ability to carry out day-to-day tasks. "Furthermore, Amano found an association between increased DSCAM expression and bipolar disorder in a genetic screen of patients with bipolar disorder." (PMID 38281050, 2024). "Altered DSCAM expression levels have been associated with several brain disorders, including DS, ASD, intractable epilepsy and bipolar disorder, and, possibly, Fragile X syndrome." (PMID 37079499, 2023). "In fact, altered DSCAM levels have been reported in multiple brain disorders, including DS, autism spectrum disorders (ASDs), intractable epilepsy, bipolar disorder, and possibly Fragile X syndrome." (PMID 37079499, 2023). "A possible involvement of the DSCAM gene in bipolar disorder has previously been reported." (PMID 22389694, 2012).
cognitive deficits (4 papers, 2015 to 2025). "As DYRK1A is a high-risk gene for ASD, previously identified genetic interaction between DSCAM and DYRK1A in DS mice sheds light on a link between DS and ASD, implicating an association of DSCAM with cognitive deficits in ASD." (PMID 40385132, 2025). "Loss of one copy of the DSCAM gene in mice reproduces autistic‐like behaviors, such as hyperactivity, motor coordination deficits, and cognitive impairment across several domains." (PMID 39294095, 2024). "In fact, DSCAM trisomy was found in a human DS patient with no signs of AD-like neuropathology, suggesting that DSCAM overexpression alone may lead to cognitive deficits, but additional studies are necessary since this patient was also trisomic for other genes on chromosome 21." (PMID 28513774, 2017).
schizophrenia (4 papers, 2012 to 2024). A major psychotic disorder characterized by abnormalities in the perception or expression of reality. "To date, the DSCAM molecule has been known implicated in neuropsychiatric disorders such as schizophrenia and autism." (PMID 38302444, 2024).